FZD8 (frizzled class receptor 8)
Diseases named in the same sentence as FZD8 in open-access papers (continued):
Sharing a sentence is not in itself a finding about the gene and the disease.
asthma (2 papers, 2015 to 2020). "According to our data, Wnt pathway involves three common DCGs including FZD8, FOXN1 and TLE2, among which only FZD8 was reported to participate in the pathogenesis of Asthma, and display abnormal expression in Chronic kidney disease." (PMID 26450611, 2015).
bladder cancer (2 papers, 2010 to 2024). "Additionally, FZD8 was the putative target of miR-99a-5p and the mimics of miR-99a-5p inhibited the proliferation, migration and invasion of bladder cancer cells via the FZD8/Wnt-b-catenin axis." (PMID 38494582, 2024). "Moreover, circMCTP2 regulated the growth and metastasis of bladder cancer cells potentially through regulating the miR-99a-5p/FZD8/Wnt-b-catenin axis." (PMID 38494582, 2024).
fibrosis (2 papers, 2022). the formation of excess fibrous connective tissue in an organ or tissue in a reparative or reactive process. "The data indicate that both TGFβ-dependent noncanonical FZD8/Wnt5B signalling and TGFβ-independent canonical β-catenin-dependent signalling may play a role in intestinal fibrosis associated with CD." (PMID 36156078, 2022).
glioblastoma (2 papers, 2019 to 2025). The most malignant astrocytic tumor (WHO grade IV). "While its function in glioblastoma remains unclear, aberrant FZD8 expression has been implicated in gastric, prostate, lung, pancreatic, and renal cancers." (PMID 40430278, 2025). "High expression of FZD1 and FZD8 has been linked to poor overall survival in glioblastoma patients." (PMID 40430278, 2025).
glioma (2 papers, 2021 to 2025). A benign or malignant brain and spinal cord tumor that arises from glial cells (astrocytes, oligodendrocytes, ependymal cells). "In low-grade glioma, FZD8 was identified as a key driver of tumor recurrence." (PMID 40430278, 2025). "The roles of FZD8, GNG12, GNB2 have not been fully illustrated in gliomas and needs further investigation." (PMID 35116059, 2021).
liver fibrosis (2 papers, 2021 to 2022). "The observed up-regulation is also consistent with the previous studies linking high FZD8 levels and WNT5B to activation of noncanonical Wnt signalling during lung and liver fibrosis." (PMID 36156078, 2022).
melanoma (2 papers, 2022 to 2024). A malignant, usually aggressive tumor composed of atypical, neoplastic melanocytes. "Due to the caveats of the specificity of the chemical inhibitors or blocking antibodies, further studies are needed to directly determine the function of FZD5 and FZD8 in melanoma." (PMID 36620565, 2022). "We therefore chose to focus on FZD4, FZD6, and FZD8 in the further experiments and treated the LECs with either control siRNA or siRNAs targeting the FZD4, FZD6, or FZD8 gene for 24 hours before the start of the 48-hour coculture with WM852 melanoma cells, followed by sorting and functional assays." (PMID 37971882, 2024). "The role of FZD5 and FZD8 in melanoma has not been studied directly." (PMID 36620565, 2022).
metastatic prostate carcinoma (2 papers, 2018 to 2022). A carcinoma that arises from the prostate gland and has spread to other anatomic sites. "Together, these observations are consistent with FZD8 as a receptor of Wnt-11 in metastatic prostate cancer." (PMID 29717114, 2018). "In addition, FZD2, FZD4, and FZD8 mRNA upregulation is also reported in human metastatic prostate cancer cell lines, and FZD2, FZD7, and FZD8 mRNA levels are increased in hormone depleted LNCaP cells." (PMID 35204808, 2022).
renal carcinoma (2 papers, 2017 to 2025). A carcinoma arising from the epithelium of the renal parenchyma or the renal pelvis. "We also investigated whether FZD8 expression was associated with aberrant Wnt pathway activation and cell proliferation, invasiveness and metastasis in renal cancer." (PMID 29108281, 2017). "We demonstrated a significant overexpression of FZD8 in primary renal cancer tissue samples when compared to their adjacent normal tissues." (PMID 29108281, 2017).
Alzheimer disease (1 paper, 2020). A progressive, neurodegenerative disease characterized by loss of function and death of nerve cells in several areas of the brain leading to loss of cognitive function such as memory and language. "The genes represented by the age‐DMRs included a few notable members such as Cyp46a1 and Abca7, which are involved in cholesterol metabolism and implicated in Alzheimer's disease, and few members of the WNT signaling and mesenchyme developmental pathways (e.g., Fzd1, Fzd8, Wnt5a, Jak3, Ptk7, Nrp2)." (PMID 32790008, 2020).
Arthritis (1 paper, 2016). Inflammation of a joint. "For example, FZD8 has been shown to regulate the canonical Wnt/β-catenin pathway in arthritis synovial fibroblasts and alveolar epithelial cell trans-differentiation in rat models." (PMID 27276676, 2016).
benign prostatic hyperplasia (1 paper, 2025). A non-cancerous nodular enlargement of the prostate gland. "Our study results, indicating lower expression of β-catenin, Fzd8, Wnt5a and cyclin D1, may suggest attenuated activity of the Wnt/β-catenin pathway in prostate adenocarcinoma compared to benign prostatic hyperplasia." (PMID 41465498, 2025). "Assessment of immunohistochemical staining intensity through digital image analysis, corroborated by statistical testing, confirmed lower immunoreactivity of β-catenin, Fzd8, Wnt5a and cyclin D1 in prostate adenocarcinoma compared to benign prostatic hyperplasia." (PMID 41465498, 2025).
cardiomyopathy (1 paper, 2022). A disease of the heart muscle or myocardium proper. "In this study, all homozygous Fzd8-null mice showed distinct features of hypertrophic cardiomyopathy with normal ECG, strongly suggesting a role for Fzd8 in cardiomyopathy." (PMID 39195995, 2022).
cervical cancer (1 paper, 2013). A primary or metastatic malignant neoplasm involving the cervix. "FZD8 was found to be highly expressed in HeLa cells and in future it would be interesting to note if targeting of FZD8 in cervical cancer cells could be helpful in overcoming resistance against TRAIL." (PMID 23773282, 2013).
chronic bronchitis (1 paper, 2021). A type of chronic obstructive pulmonary disease characterized by chronic inflammation in the bronchial tree that results in edema, mucus production, obstruction, and reduced airflow to and from the lung alveoli. "It was previously shown that elevated FZD8 expression was linked with the airway proinflammation induction and associated with chronic bronchitis." (PMID 34040530, 2021).
colorectal adenocarcinoma (1 paper, 2022). The most common type of colorectal carcinoma. "Moreover, expression of the majority of the genes (CACNA1H, COL1A1, COL11A1, FZD8, NGFR, SFRP2, WNT2B, and WNT5A) was associated with the ‘mesenchymal’ CMS group 4 in the TCGA (The Cancer Genome Atlas) Colorectal Adenocarcinoma dataset." (PMID 35892888, 2022).
gastrointestinal stromal tumor (1 paper, 2022). "FZD8 was significantly regulated by imatinib treatment in gastrointestinal stromal tumors." (PMID 36579559, 2022).
hepatocellular carcinoma (1 paper, 2021). A malignant tumor that arises from hepatocytes. "Moreover, the term “Hepatocellular carcinoma” is enriched with FZD8, ribosomal protein S6 kinase alpha-6 (PRSAKA6), TGFB3 and GSTM1." (PMID 34150612, 2021).
Hypertension (1 paper, 2024). The presence of chronic increased pressure in the systemic arterial system. "The aim of this study was to immunohistochemically evaluate and compare the expression of the Fzd8, WNT1, GSK-3β, and β-catenin genes in the hearts of rats with spontaneous hypertension (SHRs) and deoxycorticosterone acetate (DOCA)-salt-induced hypertension." (PMID 38928134, 2024).
hypertrophic cardiomyopathy (1 paper, 2022). A condition in which the myocardium is hypertrophied without an obvious cause. "For example, Fzd8- and Leprotl1-mutant mice had distinct TTE features of hypertrophic cardiomyopathy." (PMID 39195995, 2022).
leukemia (1 paper, 2013). A malignant (clonal) hematologic disorder, involving hematopoietic stem cells and characterized by the presence of primitive or atypical myeloid or lymphoid cells in the bone marrow and the blood. "Interestingly, the gene with the second highest methylation frequency in the present study, Frizzled family receptor 8 (FZD8), is involved in the Wnt signaling pathway, which is frequently altered among several cancer types, including leukemia and CRC." (PMID 24260260, 2013).
lung fibrosis (1 paper, 2022). "The results with C1 were also supported by siRNA mediated knockdown studies of FZD8 in CCD-18Co fibroblasts reported here, and studies showing that FZD8‐deficient mice are resistant to bleomycin‐induced lung fibrosis." (PMID 36156078, 2022).
lymph node metastases (1 paper, 2016). "Similarly, the expression of FZD8 protein was upregulated in both liver and lymph node metastases compared with NCTs (p=0.001 and p=0.006, respectively)." (PMID 27276676, 2016).
lymphoma (1 paper, 2013). A malignant (clonal) proliferation of B- lymphocytes or T- lymphocytes which involves the lymph nodes, bone marrow and/or extranodal sites. "The DNA methylation biomarker panel consisting of DSP, FZD8, KCNH2, and PPP1R14A was positive in 89% (54/61) of all lymphomas." (PMID 24260260, 2013). "However, this is, to the best of our knowledge, the first time DSP, FZD8, KCNH2, MTSS1, and PPP1R14A have been reported to be methylated in lymphoma." (PMID 24260260, 2013).
myocardial infarction (1 paper, 2022). Gross necrosis of the myocardium, as a result of interruption of the blood supply to the area, as in coronary thrombosis. "However, blocking Wnt receptors with monoclonal antibodies such as vantictumab and ipafricept (a fusion protein consisting of the extracellular ligand-binding domain of FZD8 and the IgG1 Fc fragment) may also be an interesting treatment strategy in myocardial infarction." (PMID 36293109, 2022).
prostate adenocarcinoma (1 paper, 2025). "Our study results revealed lower immunoreactivity and expression of genes encoding β-catenin, Fzd8, Wnt5a, and cyclin D1 and significantly higher fluorescence intensity of miRNA 106a-5p and 375-3p with prostate adenocarcinoma compared to BPH." (PMID 41465498, 2025). "Therefore, the aim of the present study was to perform a pilot evaluation of the expression of miRNAs 106a-5p and 375-3p, as well as β-catenin, Fzd8, Wnt5a, and cyclin D1 in prostate adenocarcinoma compared with BPH." (PMID 41465498, 2025). "In summary, the results of this study showed significantly higher expression of miR-106a-5p and miR-375-3p in prostate adenocarcinoma tissues compared with BPH, accompanied by lower expression of β-catenin, Fzd8, Wnt5a, and cyclin D1." (PMID 41465498, 2025). "Based on this rationale, both miRNAs were selected for our study alongside β-catenin, Fzd8, β-catenin and cyclin D1, enabling an integrated assessment of transcript and protein expression patterns in BPH and prostate adenocarcinoma specimens." (PMID 41465498, 2025).
prostate tumors (1 paper, 2018). "We further show that both Wnt-11 and FZD8 protein levels are higher in prostate tumor cells than in prostate epithelial cells in benign tissue, consistent with a role for FZD8 in transducing autocrine Wnt-11 signals." (PMID 29717114, 2018).
small cell lung carcinoma (1 paper, 2015). Small cell lung cancer (SCLC) is a highly aggressive malignant neoplasm, accounting for 10-15% of lung cancer cases, characterized byrapid growth, and early metastasis. "Moreover, we performed dual luciferase reporter assay and Western blot on 6 targeted genes (FZD8, ITGA10, ITPKB, LRP5, PIAS1 andRUNX1) in small cell lung carcinoma cell line NCI-H82." (PMID 26642205, 2015).
spine osteoarthritis (1 paper, 2022). "Our data showed that miR-99a alleviated apoptosis and extracellular matrix degradation by targeting FZD8, and thereby suppressed the development and progression of experimentally induced spine osteoarthritis." (PMID 36127685, 2022). "Collectively, our results suggest that overexpression of miR-99a might alleviate cartilage injury in experimentally induced spine osteoarthritis via the FZD8/β-catenin pathway." (PMID 36127685, 2022).
cancer (37 papers, 2009 to 2023). A tumor composed of atypical neoplastic, often pleomorphic cells that invade other tissues. "For example, Fzd8 and pcdhs which are associated to Wnt signaling, an evolutionarily conserved regulatory pathway related to cell fate determination and proliferation during development, have also been identified as part of a key mechanism in cancer biology." (PMID 34306008, 2021). "FZD8 is methylated early in the development of AML, suggesting there may be specific contexts where FZD8 loss supports cancer development and that targeted re-expression of FZD8 could be a chemoprevention strategy." (PMID 34604862, 2021). "RCC tissues that successfully generated organoids highly expressed genes associated with stemness (WNT6/11, FZD8/9 and JAG2), cell matrix (MMP2, COL1A1), fatty metabolism (ACOT2, LIPE) and cancer development (TGFB1, SMAD6/7, EGF and FGF1)." (PMID 35802820, 2022). "By targeting miR-370-3p, Circ-NEK6 promotes cancer cell invasion, metastasis, and disease progression via transmembrane signaling receptor “frizzled family receptor 8 (FZD8)” upregulation and “Wnt signaling” pathway activation in TC." (PMID 36230649, 2022). "FZD8 is a G protein-coupled receptor protein that plays an important role in β-catenin signaling pathway and regulates cancer invasion and metastasis." (PMID 35116059, 2021). "Carbamazepine, an antiepileptic drug, was recently reported to bind the cysteine-rich domain of FZD8, which suggested to been explored as a promising therapy option in cancers." (PMID 33276800, 2020). "As anticipated, our data showed that the overexpression of miR-375 significantly inhibited the Wnt/β-catenin pathway and downregulated FZD8, which consequently decreased cancer cell invasion and metastasis." (PMID 27276676, 2016). "Interestingly, carbamazepine, an antiepileptic drug, was recently reported to bind the cysteine-rich domain of FZD8, which suggests been explored as a promising therapy option in cancers." (PMID 33276800, 2020). "Analysis of patient samples reveals increased levels of FZD8 in cancer, correlating with Wnt-11." (PMID 29717114, 2018). "FZD8 and Wnt-11 were also both significantly lower in tumor stroma than in the benign stroma, suggesting that elevated expression in cancer epithelial cells is accompanied by reduced expression in tumor-associated stroma." (PMID 29717114, 2018). "Because FZD8 is a key receptor for the initiation of Wnt/β-catenin signaling pathway, which is well known for its role in the development and promotion of cancer metastasis, we investigated the ability of miR-375 to regulate Wnt/β-catenin signaling by inhibiting FZD8 expression." (PMID 27276676, 2016). "FZD8, a member of the Frizzled receptor family, might activate canonical or non-canonical Wnt signaling, and dysregulation of the Wnt signaling pathway and/or of Hippo pathway components has been described in several types of cancer." (PMID 35269556, 2022). "FZD8 could activate the β-catenin pathway and play a vital role in cancer invasion and metastasis." (PMID 35116059, 2021). "Of the EMT pathway, the genes IL-6, SFRP4, FZD8, ADAM12, and CCN2 are known to promote cancer cell invasion and migration in multiple types of cancers." (PMID 35505422, 2022). "Members in FZD family including FZD2, FZD4, FZD7, FZD8 and FZD10 have been demonstrated to mediate cancer cell epithelial-mesenchymal transition (EMT)." (PMID 33618713, 2021). "The prominent role of FZD8 in EMT and its potential involvement in premalignant lesion development present a favorable drug target for cancer chemoprevention." (PMID 34604862, 2021). "Beyond this, the pathway in cancer revealed that most of the genes are relative to WNT pathway (WNT7B, WNT6, WNT10B, FZD6, FZD8, and LPAR5), and among these, WNT7B, WNT10B, FZD6, FZD8, and LPAR5 belonged to the classical WNT pathway." (PMID 34122668, 2021).
cancer (continued). "MET increased the expression of FZD8 via the ERK/c-Fos cascade in the cancer stem-like cells (CSC) of head and neck squamous carcinomas (HNSCC), and Wnt pathway receptor FZD8 was necessary for interplay between MET and Wnt/β-catenin signaling." (PMID 29108281, 2017). "For example, genes with Motif 1 in Molecular Mechanisms of Cancer pathway include MAPK1, BRAF, SMAD2, FZD5, FZD8, NOTCH1 and LRP1, whereas genes with Motif 2 and/or Motif3 in the same pathway include LRP5, LRP6, MDM2, CTNND1, SMAD3, SMAD4 and SMAD7." (PMID 26040697, 2015). "FZD8, WIF1 and SOX7 were identified by HTself as differentially expressed between cancer and luminal cells, and in whole tissue CP compared to NP." (PMID 20021671, 2009). "Frizzled-8 (FZD8) as a Wnt receptor is known to be necessary for the interaction between the Wnt/β-catenin axis and c-Met since it is upregulated through the ERK/c-Fos cascade by c-Met in cancer stem-like cells." (PMID 35986321, 2022). "FZD8, plasminogen activator, urokinase receptor, ITGA2, WNT2B, TIMP3, WNT5B, FGF5, heparanase, HBEGF and WNT3A were up-regulated in the proteoglycan pathways in cancer, whereas WNT10A, PIK3R3, IGF2 were down-regulated." (PMID 30482199, 2018). "Fifteen members of cancer pathways, including FOS, TGFα, FZD8, MMP1, laminin subunit gamma 2, PTGS2, laminin subunit beta 3, ITGA2, laminin subunit alpha 3, VEGFC, WNT2B, heat shock protein 90 beta family member 1, WNT5B, FGF5 and WNT3A, were up-regulated in the MC group." (PMID 30482199, 2018). "Nonetheless, attempts to therapeutically inhibit FZD8 have failed so far due to lack of therapeutic index, suggesting that FZD8 may not be involved in promoting cancer growth." (PMID 31879968, 2020). "In the cancer cells as well as cancer cell lines (data not shown), there was increased expression of Wnt receptor FZD8; decreased expression of Wnt inhibitor WIF1, which functions to sequester Wnt molecules from receptor binding, and that of the transcription factor SOX7." (PMID 20021671, 2009). "FZD8 was shown up-regulated in CD26+ G3 cancer cells, and the GSE6099 dataset also showed agreement; GSE5132 contained no information regarding FZD8." (PMID 20021671, 2009).